FBXO32 (F-box protein 32)
Diseases named in the same sentence as FBXO32 in open-access papers (continued):
Sharing a sentence is not in itself a finding about the gene and the disease.
ovarian cancer (8 papers, 2015 to 2025). A primary or metastatic malignant neoplasm involving the ovary. "FBXO32 promoter hypermethylation has been revealed to be linked to poor prognosis in patients with ovarian cancer." (PMID 35928868, 2022). "From previous evidence, promoter hypermethylation-mediated loss of FBXO32 expression was linked with poor patient survival in human ovarian cancer." (PMID 33585183, 2020). "Strikingly, linc00494 expression levels were highly upregulated in ovarian cancer tissues, while FBXO32 has a lower expression in ovarian tumor specimens." (PMID 35928868, 2022). "FBXO32 can be modulated by LINC00494 to facilitate ovarian cancer progression via binding with NF-κB." (PMID 36293081, 2022). "The promoter hypermethylation of FBXO32 was responsible for its downregulation in ovarian cancer cells." (PMID 35046938, 2021). "The re-expression of FBXO32 dampened cell growth in platinum-resistant ovarian cancer as a result of being re-sensitized to cisplatin and increased apoptosis." (PMID 35046938, 2021). "As a tumor suppressor and a TGF-β/SMAD4 target gene, methylation of FBXO32 promoter correlates with poor ovarian cancer prognosis while reintroduction of FBXO32 can sensitize the cells to cisplatin treatment." (PMID 35582023, 2021). "Our work demonstrated that LINC00494 promoted ovarian cancer progression by modulating FBXO32 via binding with the transcription factor NFκB1." (PMID 33585183, 2020). "Overexpression of LINC00494 elevated NFκB1 expression and enhanced cell migration, invasion and tumorigenesis, but additional overexpression of FBXO32 interfered with the tumorgenicity of ovarian cancer cells in vitro and in vivo." (PMID 33585183, 2020). "We performed real-time qPCR and immunoblotting analysis to determine the expression levels of LINC00494, NFκB1, and FBXO32 in several ovarian cancer cell lines (Caov-3, A2780, SKOV3, and CoC1) and a normal ovarian epithelial cell line, IOSE80." (PMID 33585183, 2020). "In this study, we found that LINC00494 can bind to the transcription factor NFκB1, and that NFκB1 then binds to the FBXO32 promoter, aggravating ovarian cancer." (PMID 33585183, 2020). "The differentially analysis indicated high expression of LINC00494 and low expression of FBXO32 in ovarian cancer, which was entirely consistent with corresponding findings in clinical cancer tissues and normal tissues." (PMID 33585183, 2020). "LINC00494 and NFκB1 were highly expressed whereas FBXO32 had low expression in ovarian cancer cells and tissues." (PMID 33585183, 2020). "Bioinformatics analysis predicted potential interactions among LINC00494, NFκB1, and FBXO32 in ovarian cancer, which were tested by dual-luciferase reporter assay, RNA pull-down, RIP, and ChIP assay." (PMID 33585183, 2020). "Our previous studies demonstrated that novel TGF-β targets, FBXO32 and RunX1T1, are epigenetically silenced by promoter hypermethylation in ovarian cancer." (PMID 25628764, 2015). "Moreover, LINC00494 has been found to promote ovarian cancer advancement by regulating FBXO32 via binding and enhancing the activity of the NF-kappaB1 (NF-κB1)." (PMID 40181954, 2025). "In summary, linc00494 modulated NF-kappa B1 and FBXO32 and enhanced progression of ovarian cancer." (PMID 35928868, 2022). "Accordingly, further mechanistic investigations showed that LINC00494 recruited transcription factor NFκB1 to bind on the promoter region of FBXO32, which inhibited the transcription of FBXO32, while suppressing the progression and development of ovarian cancer." (PMID 33585183, 2020). "Therefore, we performed this study to define better the regulatory role of the LINC00494/NFκB1/FBXO32 axis in the development of ovarian cancer." (PMID 33585183, 2020). "Our study aim was to study the effects of FBXO32 on ovarian cancer cells and investigate whether FBXO32 is responsible for the regulation of LINC00494 on ovarian cancer cells." (PMID 33585183, 2020).
ovarian cancer (continued). "Moreover, recent research identifies FBXO32 as a functional tumor suppressor, whereby re-expression of epigenetically silenced FBXO32 in ovarian cancer cells facilitates cell sensitivity to cisplatin." (PMID 33585183, 2020). "Additionally, FBXO32 was found to inhibit the proliferation of the ovary cancer cell SKOV3." (PMID 37175415, 2023). "However, due to the limited time and funding, we are not allowed to explore the respective roles of FBXO32 and NFκB1 in ovarian cancer, which will be further studied in our future research for better clinical application of LINC00494 knockdown." (PMID 33585183, 2020).
lung carcinoma (7 papers, 2022 to 2024). "The expression levels of proteolysis-related genes such as Trim63 and Fbxo32 (also known as Atrogin1) are upregulated in the lung cancer-induced cachectic muscle." (PMID 35406121, 2022). "Furthermore, we found that patients with lymph node metastases or advanced lung cancer are more likely to display higher protein levels of FBXO32." (PMID 38643215, 2024). "FBXO32 could promote the proliferation of lung cancer cells." (PMID 37175415, 2023). "The results showed that FBXO32 and FOXK2 were significantly co‐expressed in epithelial cells of lung cancer STAD, and BLCA." (PMID 39552461, 2024).
pancreatic cancer (6 papers, 2021 to 2024). "Evidence suggests that FBXO32 is significantly involved in the progression of different types of cancers, such as pancreatic cancer and lung adenocarcinoma." (PMID 39552461, 2024).
type 2 diabetes (6 papers, 2013 to 2025). "Nine genes not previously reported to be associated with type 2 diabetes were significantly dysregulated in our organ donor and PPP cohorts (ANKRD23/39, ASCL2, HHATL, NSG1, PCDH20, SCTR, CD44, FAM102B and FBXO32)." (PMID 29185012, 2018).
colorectal cancer (4 papers, 2019 to 2025). A primary or metastatic malignant neoplasm that affects the colon or rectum. "This showed that the treatment of colorectal cancer cells with Lb. plantarum AY01 can correct the expression of FBXO32, KLHL21, and WDR34." (PMID 39132155, 2024). "Moreover, high FBXO32 expression was found to reflect higher five-year overall survival of patients with colorectal cancer." (PMID 31810245, 2019). "FBXO32, KLHL21, and DYNC2H1 were significantly downregulated and WDR34 was significantly upregulated in colorectal cancer patients." (PMID 39132155, 2024).
gastric cancer (4 papers, 2018 to 2025). A primary or metastatic malignant neoplasm involving the stomach. "EZH2, a histone lysine N-methyltransferase responsible for mediating histone methylation and transcriptional repression, plays a role in the resistance of gastric cancer cells to 5-fluorouracil (5-FU) by suppressing FBXO32 expression." (PMID 40534867, 2025). "A high expression of Fbxo32 has been found in muscle atrophy, while lower expression contributes to tumorigenesis in gastric cancer and cervical neoplastic keratinocytes." (PMID 33829047, 2021). "FBXO32 expression is significantly downregulated in 5-FU-resistant gastric cancer cells." (PMID 40534867, 2025). "Interestingly, knockdown of FBXO32 enhances the cytotoxic effects of 5-FU in gastric cancer cells that have developed prior resistance to the drug." (PMID 40534867, 2025). "For instance, KHDRBS3 was found to interact with FBXO32 mRNA to promote gastric cancer progression." (PMID 37848941, 2023).
Stroke (4 papers, 2020 to 2021). Sudden impairment of blood flow to a part of the brain due to occlusion or rupture of an artery to the brain. "Our initial qPCR findings indicated both Atrogin-1 (Fbxo-32) and MuRF1 (Trim63) to be significantly upregulated in response to stroke." (PMID 32629989, 2020).
glioma (3 papers, 2012 to 2023). A benign or malignant brain and spinal cord tumor that arises from glial cells (astrocytes, oligodendrocytes, ependymal cells). "Although there was no significant change in muscle weight was found, the expression of E3 ligases Trim63 and Fbxo32 was increased in the muscle of mice bearing IDH1 mutant glioma tumors, whereas it was attenuated after ivosidenib treatment." (PMID 37741882, 2023). "Surprisingly, p27, p21, p16, FBXO32, EED, Cyclin E and TGF-β-1 were not induced in EZH2 knockdown cells further suggesting that EZH2 influences the motile phenotype of glioma cells independent of histone methylation." (PMID 23077658, 2012).
lung adenocarcinoma (3 papers, 2024 to 2025). A carcinoma that arises from the lung and is characterized by the presence of malignant glandular epithelial cells. "It is known that FBXO32 promotes the epithelial-mesenchymal transition in cancer including lung adenocarcinoma." (PMID 41187747, 2025). "Thereby, targeting FBXO32 is a promising potential therapeutic strategy to inhibit the progression of lung adenocarcinoma and improve the prognosis of patients." (PMID 38643215, 2024). "Our study reveals that FBXO32 promotes lung adenocarcinoma progression by degrading PTEN via ubiquitination." (PMID 38643215, 2024). "However, the functions and the molecular mechanisms regulated by FBXO32 in lung adenocarcinoma (LUAD) remain unclear." (PMID 38643215, 2024). "In summary, our study highlights the role of FBXO32 in promoting the PI3K/AKT/mTOR pathway via PTEN degradation, thereby fostering lung adenocarcinoma progression." (PMID 38643215, 2024). "In the future, the combination of FBXO32 inhibitors with PI3K/AKT/mTOR inhibitor may be a potential way to reduce drug resistance and toxicity in lung adenocarcinoma." (PMID 38643215, 2024). "Besides, we extracted cytoplasmic protein and cell membrane protein of lung adenocarcinoma cells respectively and found that FBXO32 and PTEN were co-expressed in the cytoplasm rather than in the cell membrane." (PMID 38643215, 2024).
ovarian tumor (3 papers, 2016 to 2025). "However, the expression of F-box protein 32 (FBXO32) was found to increase with ovarian tumor progression, and its expression was also observed to be increased with a shorter recurrence period after chemotherapy." (PMID 31810245, 2019).
Alzheimer disease (2 papers, 2020 to 2021). A progressive, neurodegenerative disease characterized by loss of function and death of nerve cells in several areas of the brain leading to loss of cognitive function such as memory and language. "We suppose that it may explain the upregulation of FBXO32 in several brain regions in Alzheimer’s disease." (PMID 32433480, 2020).
atrial fibrillation (2 papers, 2021 to 2023). A disorder characterized by an electrocardiographic finding of a supraventricular arrhythmia characterized by the replacement of consistent P waves by rapid oscillations or fibrillatory waves that vary in size, shape and timing and are accompanied by an irregular ventricular response. "Analysis of the link between atrial cell differentiation and atrial fibrillation singled out known risk genes, such as MYH6 and FBXO32." (PMID 34194671, 2021).
esophageal squamous cell carcinoma (2 papers, 2019 to 2021). Esophageal squamous cell carcinoma (ESCC) is a type of esophageal carcinoma (EC) that can affect any part of the esophagus, but is usually located in the upper or middle third. "FBXO32 is also known to be inactivated in gastric cardia adenocarcinoma and esophageal squamous cell carcinoma." (PMID 31810245, 2019). "A similar situation of aberrant methylation of FBXO32 could be found in esophageal squamous cell carcinoma." (PMID 35046938, 2021).
Hyperinsulinemia (2 papers, 2011 to 2023). An increased concentration of insulin in the blood. "Muscle atrogenes such as MuRF1/Trim63 and Atrogin1/Fbxo32 were downregulated in ob/ob GRfl/fl mice compared with lean GRfl/fl mice, possibly reflecting the counteracting role of hyperinsulinemia in ob/ob mice for maintaining muscle mass." (PMID 36917179, 2023).
ischemia (2 papers, 2022 to 2024). A hypoperfusion of the BLOOD through an organ or tissue caused by a PATHOLOGIC CONSTRICTION or obstruction of its BLOOD VESSELS, or an absence of BLOOD CIRCULATION. "The FBXO32 gene is a key mediator of apoptosis following ischemia injury, and apoptosis can lead to tissue damage that requires the activation of repair mechanisms." (PMID 39199913, 2024).
ischemic stroke (2 papers, 2020 to 2022). A stroke disorder caused by obstruction of blood flow to the brain, due to thrombotic (local blood clot formation) or embolic (due to a blood clot or other material traveling from another site) event. "Previously, it has been shown that ischemic-stroke-induced skeletal muscle atrophy occurs in tandem with the upregulation of various genes related to the ubiquitin–ligase pathway, such as Atrogin-1 (Fbxo32) and MuRF1 (Trim63)." (PMID 32629989, 2020).
lentivirus infection (2 papers, 2021 to 2023). Virus diseases caused by the Lentivirus genus. "Through lentivirus infection method, FBXO32 downregulation in hDPSCs attenuated odontoblastic differentiation in vitro and in vivo, whereas FBXO32 upregulation promoted the hDPSCs odontoblastic differentiation, without affecting proliferation and migration." (PMID 37175415, 2023). "Conversely, forced expression of FBXO32 in SKmel28 cell line, by lentivirus infection, increased the formation of colonies." (PMID 33462405, 2021).
pancreatic adenocarcinoma (2 papers, 2021). "The mRNA expression levels of RUNX2, LAMC2 and FBXO32 showed significant differences between cancer and adjacent non-cancerous tissues especially in pancreatic adenocarcinoma (PAAD)." (PMID 34606473, 2021).
breast tumor (1 paper, 2017). "To ultimately validate these findings in clinical samples, we collected non-invasive and invasive breast tumor samples (n = 20 each) and analyzed the expression of FBXO32 in these samples." (PMID 29142217, 2017). "A survival analysis of the clinical breast tumor data sets revealed a significant correlation between higher FBXO32 expression and poor relapse-free and metastasis-free survival." (PMID 29142217, 2017). "Our analysis showed a massive amplification of FBXO32 in several tumor types which was very strong for most breast tumor datasets." (PMID 29142217, 2017).
Co-infection (1 paper, 2025). "Additionally, FBXO32 was also upregulated in the caudal fin of Mc+ fish, reflecting similar stress responses and metabolic adjustments in peripheral tissues during co-infection." (PMID 40943072, 2025).
coronary heart disease (1 paper, 2015). "We examined the plasma Rnf207, Fbxo32, Trim54, Trim63, Kbtbd10 and Asb11 in three groups (the AMI, coronary heart disease (CHD) and healthy groups)." (PMID 25599194, 2015).
deafness (1 paper, 2019). An inherited or acquired condition characterized by the complete loss of the ability to hear from one or both ears. "Although a subset of genes that related to IHC machinery and deafness were found to be differentially expressed, a gradient of gene expression was indeed detected in Ocm, Pvalb, Prkd1, Fbxo32, Nme2, and Sncg, which may play putative roles in the Ca2+ buffering and survival regulation." (PMID 32038162, 2019).
dysplastic nevi (1 paper, 2021). "Additional analysis of FBXO32 expression in the GSE12391 cohort, containing different stages of the disease, including nevi, dysplastic nevi, primary, and metastatic melanomas, showed that FBXO32 expression was increased in metastatic melanoma as compared to earlier stages." (PMID 33462405, 2021).
hepatocellular carcinoma (1 paper, 2025). A malignant tumor that arises from hepatocytes. "F‐Box Protein 32 (FBXO32) is markedly overexpressed in hepatocellular carcinoma and facilitates tumor progression by activating the PI3K–AKT signaling pathway via PHLPP2 degradation, underscoring its potential as a promising therapeutic target." (PMID 41000374, 2025).
Hypoxemia (1 paper, 2022). An abnormally low level of blood oxygen. "Hypoxemia-induced muscle wasting was shown to increase MuRF1/Trim63 and atrogin-1/Fbxo32 expression possibly mediating muscle wasting." (PMID 35615361, 2022).
liver cancer (1 paper, 2025). An epithelial or non-epithelial malignant neoplasm that arises from the liver. "FBXO32 expression was also progressively elevated in advanced stages of liver cancer." (PMID 41000374, 2025). "Our outcomes indicated that FBXO32 was significantly overexpressed in liver cancer cells." (PMID 41000374, 2025). "Additionally, FBXO32 overexpression was significantly pertaining to poor overall survival (OS) in liver cancer patients." (PMID 41000374, 2025).
lymph node metastasis (1 paper, 2024). "In our study, we discovered that FBXO32 was significantly and highly expressed in LUAD and was positively associated with lymph node metastasis and poor patient prognosis." (PMID 38643215, 2024).
metastatic cancers (1 paper, 2017). A carcinoma which has spread from the original site of growth to another anatomic site. "Extending these findings to cancer metastasis as an example of disease EMT, we found that FBXO32 was strongly amplified in metastatic cancers, and its depletion in a NSG mouse xenograft model significantly inhibited tumor growth and metastasis." (PMID 29142217, 2017). "FBXO32 is also amplified in metastatic cancers and its depletion in a NSG mouse xenograft model inhibits tumor growth and metastasis." (PMID 29142217, 2017).
Mondini dysplasia (1 paper, 2017). "As examples, the mutation of SOX10 (R109W) in pig causes inner ear malfunctions and mimics human Mondini dysplasia, and upregulated expression of FBXO32 is associated with congenital splay legs." (PMID 28639938, 2017).
multiple myeloma (1 paper, 2023). "However, FBXO32 overexpression in two multiple myeloma cell lines reduced cell proliferation and enhanced cell apoptosis." (PMID 37175415, 2023).
prostate carcinoma (1 paper, 2012). A carcinoma that arises from epithelial cells of the prostate gland. "SKAP1 (rs6504145) in Han Chinese populations was detected to affect prostate cancer specific mortality in advanced prostate cancer populations, and variation in FBXO32 (rs7830622) and FLT1 (rs9508016) appeared to affect all-cause mortality in advanced prostate cancer." (PMID 22956944, 2012).
sarcoma (1 paper, 2026). A usually aggressive malignant neoplasm of the soft tissue or bone. "DMBA injection produced sarcoma-like tumors, reduced body weight, elevated inflammatory mediators, and activated muscle atrophy genes (Fbxo32)." (PMID 41828598, 2026).